SLC39A13 (solute carrier family 39 member 13)
Description:
Functions as a zinc transporter transporting Zn(2+) from the Golgi apparatus to the cytosol and thus influences the zinc level at least in areas of the cytosol. May regulate beige adipocyte differentiation (By similarity).
Synonyms: LZT-Hs9; ZIP-13; ZIP13; FLJ25785; EDSSPD3; SCDEDS
Tractability: Antibody: UniProt predicts a signal peptide or a membrane-spanning region.
Gene: Protein-coding gene on chromosome 11 (47,407,132 to 47,416,587, forward strand). Ensembl gene ENSG00000165915.
Subcellular location: Golgi apparatus membrane; Cytoplasmic vesicle membrane; Endoplasmic reticulum membrane
Gene Ontology:
Molecular function: protein binding; protein homodimerization activity; zinc ion transmembrane transporter activity; metal ion transmembrane transporter activity
Biological process: connective tissue development; intracellular zinc ion homeostasis; zinc ion transmembrane transport; zinc ion transport; brown fat cell differentiation; metal ion transport; transmembrane transport
Cellular component: cytoplasmic vesicle membrane; endoplasmic reticulum membrane; Golgi apparatus; Golgi membrane; membrane; perinuclear region of cytoplasm
Genetic constraint (gnomAD): Loss-of-function variants: 18 observed, 40.33 expected, observed/expected ratio (o/e) 0.45, 90% interval 0.31 to 0.66. The upper end of that interval is the gene's LOEUF score, 0.66, which puts it in group 2 of 6, group 1 being the genes least tolerant of losing a copy. Missense variants: 395 observed, 511.77 expected, observed/expected ratio (o/e) 0.77, 90% interval 0.71 to 0.84. Synonymous variants: 212 observed, 227.31 expected, observed/expected ratio (o/e) 0.93, 90% interval 0.83 to 1.04.
Gene-disease validity (ClinGen):
ClinGen rates the evidence that SLC39A13 causes each of these diseases.
Ehlers-Danlos syndrome, spondylocheirodysplastic type (autosomal recessive): Definitive.
Homologues: Orthologues: chimpanzee SLC39A13 (98% identical), macaque SLC39A13 (97% identical), pig SLC39A13 (91% identical), rabbit SLC39A13 (90% identical), rat Slc39a13 (89% identical), mouse Slc39a13 (88% identical), guinea pig SLC39A13 (82% identical), dog SLC39A13 (67% identical), tropical clawed frog slc39a13 (57% identical), zebrafish slc39a13 (54% identical), Drosophila melanogaster Zip99C (42% identical), Caenorhabditis elegans zipt-13 (33% identical). Paralogues in human: SLC39A7 (35% identical).
Diseases named in the same sentence as SLC39A13 in open-access papers:
SLC39A13 is named in the same sentence as 57 diseases in open-access papers, as found by Europe PMC text mining. Sharing a sentence is not in itself a finding about the gene and the disease. The quoted sentences say what the papers report.
Ehlers-Danlos syndrome (16 papers, 2008 to 2025). The Ehlers–Danlos syndromes (EDS) are a clinically and genetically heterogeneous group of heritable connective tissue disorders (HCTDs) characterized by joint hypermobility, skin hyperextensibility, and tissue fragility. "Loss of function mutations of SLC39A13 have been demonstrated to cause an autosomal recessive disease called spondylocheirodysplastic form of Ehlers-Danlos syndrome (SCD-EDS)." (PMID 35745255, 2022). "Mutations in this gene cause a form of Ehlers-Danlos syndrome, a group of connective tissues disorders that affect the vasculature and can cause stroke;52 vascular abnormalities have been reported in SLC39A13-knockout mice." (PMID 33773637, 2021). "Here we report that mice deficient in Zn transporter Slc39a13/Zip13 show changes in bone, teeth and connective tissue reminiscent of the clinical spectrum of human Ehlers-Danlos syndrome (EDS)." (PMID 18985159, 2008). "In this study, we focused on the zinc transporter ZIP13 because Zip13-deficient (Zip13-KO) mice and humans with spondylocheirodysplastic Ehlers-Danlos syndrome who carry a loss-of-function mutation in SLC39A13 have been reported to have a significantly decreased white fat mass." (PMID 28854265, 2017). "Mutations in SLC39A13, encoding ZIP13, cause a novel subtype of Ehlers-Danlos Syndrome (EDS)." (PMID 28629136, 2017). "As leading examples, mutations in ZIP4 (SLC39A4) and ZIP13 (SLC39A13) are responsible for the rare lethal autosomal-recessive inherited zinc deficiency disease, acrodermatitis enteropathica (AE), and Ehlers-Danlos Syndrome (EDS), respectively." (PMID 30417019, 2018).
ovarian carcinoma (6 papers, 2021 to 2025). A malignant neoplasm originating from the surface ovarian epithelium. "SLC39A4 and SLC39A13 (ZIP13) have been implicated in ovarian cancer progression and metastasis." (PMID 40362545, 2025). "Knockdown of SLC39A13 similarly hampers the migration and invasion of ovarian cancer cells." (PMID 41583444, 2025). "In ovarian cancer, SLC39A13 (ZIP13) and ZIP5, ZIP10, ZIP12 and ZIP14 overexpression were found to be associated with poor prognosis, and SLC39A13 knockout demonstrated suppression of the malignant phenotype in vitro and in vivo and a higher vesicular zinc level in knockout cells." (PMID 35625809, 2022).
Zinc deficiency (5 papers, 2010 to 2024). A deficiency of the essential metal Zinc; an essential cofactor for many enzymes. "Dlx5 has been shown to induce expression of Runx2 in chicken, and Runx2, which is important for osteogenic differentiation, was recently found to be downregulated during zinc deficiency, and abnormally accumulated in osteoblasts from Slc39a13 null mice." (PMID 20937081, 2010). "SLC39A13, a member of the SLC39A family of zinc transporters, responsible for zinc influx, is over-expressed in kidney during dietary zinc deficiency in Wistar rats, playing a role in transporting zinc into cells to avoid zinc depletion." (PMID 38858654, 2024).
acrodermatitis enteropathica (4 papers, 2018 to 2019). Acrodermatitis enteropathica (AE) is a rare inherited inborn error of metabolism resulting in a severe zinc deficiency and characterized by acral dermatitis, alopecia, diarrhea and growth failure. "Similarly, mutations in SLC39A4 (ZIP4) and SLC39A13 (ZIP13) have been linked to Zn deficiency and/or accumulation in specific cellular compartments resulting in acrodermatitis enteropathica and spondylocheiro dysplastic Ehlers-Danlos syndrome, respectively." (PMID 29621230, 2018).
spondylodysplastic EDS (3 papers, 2017 to 2020). "Two of these LKs, GalT-I- and GalT-II-deficiency, fit with the EDS spectrum and are recognized in the 2017 EDS nosology as spondylodysplastic EDS (spEDS) that also includes patients with mutations in SLC39A13 encoding the ZIP13 protein involved in the influx of zinc into the cytosol." (PMID 31438591, 2019).
Alcohol Use Disorder (2 papers, 2019). "Although below the suggestive significant threshold in this rare-variant gene test, SLC39A13 has recently been identified as a novel locus for alcohol use disorder identification test (AUDIT) total score in the UK Biobank13." (PMID 30718457, 2019).
myopia (2 papers, 2020 to 2023). "An additional eGene, the zinc transporter encoding gene SLC39A13, is mutated in spondylodysplastic Ehlers–Danlos syndrome (OMIM 612350), a rare syndrome with multi-tissues manifestations: skeletal dysplasia, blue sclera, muscular hypotonia, and ocular impairments that include myopia and keratoconus." (PMID 37621707, 2023). "Eye findings—Myopia has been reported in several SLC39A13 patients and also seems to be a direct (though non-specific) manifestation of the primary genetic defect." (PMID 32295219, 2020).
Osteopenia (2 papers, 2008 to 2021). Osteopenia is a term to define bone density that is not normal but also not as low as osteoporosis. "Homozygous Slc39a13 knockout (Slc39a13-KO) mice showed growth retardation, progressive kyphosis after 3–4 weeks of age, osteopenia, and abnormal cartilage development." (PMID 34712265, 2021). "Slc39a13-KO mice show osteopenia due to the reduction of osteoblast activity." (PMID 18985159, 2008).
achondroplasia (1 paper, 2008). Achondroplasia is the most common form of chondrodysplasia, characterized by rhizomelia, exaggerated lumbar lordosis, brachydactyly, and macrocephaly with frontal bossing and midface hypoplasia. "The gain-of-function mutant of Fgfr3 causes achondroplasia, Sox9 controls chondrocyte differentiation via Sox5 and Sox6 expression, and Ihh is a master gene of bone development under BMP control, suggesting that Slc39a13 exerts a profound influence on genes crucial to chondrocyte differentiation." (PMID 18985159, 2008).
cerebral small vessel disease (1 paper, 2025). Cerebral small vessel disease is the term currently used to pathological processes that affect the brain parenchymal circulation (arterioles, capillaries, and veins). "Further, consistent with findings that AD and VaD often co-exist, our AD TWAS identified genes that were associated with lacunar and ischemic strokes, as well as cerebral small vessel disease in other studies, including SLC39A13, RAPSN, MAF1, and MME." (PMID 40141087, 2025).
Fine-Lubinsky syndrome (1 paper, 2023). A syndrome characterized by psychomotor delay, brachycephaly with flat face, small nose, microstomia, cleft palate, cataract, hearing loss, hypoplastic scrotum and digital anomalies. "Two patients referred with Fine Lubinsky syndrome and found to have pathogenic variants in POR and SLC39A13, respectively, had their clinical diagnoses changed to Antley-Bixler and spondylocheiro-dysplastic Ehlers-Danlos syndromes, respectively." (PMID 37946251, 2023).
kidney damage (1 paper, 2024). "The SLC39A13-rs10742802 variant was associated with kidney damage and the serum variables eGFRCrea, eGFRCreaCysC, SCr and SCysC in both the Overall and Non-Diabetic Cohorts." (PMID 38858654, 2024). "The SLC39A13-rs10742802 variant, in strong LD with SLC39A13-rs2293576 (R2 = 0.7632) was also associated with Kidney Damage and the serum variables eGFRCrea, eGFRCreaCysC, SCr and SCysC." (PMID 38858654, 2024). "We confirmed the influence of several known NEMG on kidney disease and function and found novel associations for SLC39A13, CFL1, ACP2 or ATP5G1 with serum variables and kidney damage, and for SLC4A1, NUP210 and MYH14 with ESKD." (PMID 38858654, 2024). "Among the NEMG predictive of kidney damage along with serum phenotypes in our patients (NOS3, ACP2 and SLC39A13), some of them have previously been linked to kidney disease." (PMID 38858654, 2024).
lymph node metastasis (1 paper, 2020). "For patients with positive lymph node metastasis, SLC39A2, SLC39A3, SLC39A7, SLC39A8, SLC39A12 and SLC39A13 high expression suggested a worse OS, but SLC39A10 high expression suggested a benefit OS." (PMID 32744318, 2020).
microstomia (1 paper, 2019). "Wide forehead, hypertelorism, and microstomia are more common in B4GALT7-spEDS, whereas frontal bossing, micrognathia, and abnormal dentition characterize B3GALT6- and SLC39A13-spEDS." (PMID 31438591, 2019).
schizophrenia (1 paper, 2017). A major psychotic disorder characterized by abnormalities in the perception or expression of reality. "While this review emphasizes the role of the SLC39A13 gene, recent studies have shed light on additional zinc transport genes linked to schizophrenia." (PMID 28713269, 2017). "In one study, a disruptive de novo mutation was identified in the zinc transport gene SLC39A13 in a sporadic schizophrenia case compared to healthy parents." (PMID 28713269, 2017). "One particular SLC39A13 mutation is linked to spondylocheiro dysplastic-Ehlers–Danlos syndrome, a condition which includes spine and hand dysplasia and can also entail significant psychopathology, including schizophrenia, in association with joint hypermobility." (PMID 28713269, 2017).
vascular EDS (1 paper, 2020). "Thus, analogy between SLC39A13 deficiency and vascular EDS may include vascular fragility as well as a moderate resemblance of facial features." (PMID 32295219, 2020).
cancer (6 papers, 2019 to 2025). A tumor composed of atypical neoplastic, often pleomorphic cells that invade other tissues. "SLC39A2 and SLC39A13 were found not differentially expressed between cancer tissues and normal tissues, but highly expressed of which also indicated poorer prognosis of LUAD patients." (PMID 33535184, 2021).
connective tissue disorder (6 papers, 2008 to 2024). A disease involving the connective tissue. "Ehlers–Danlos syndrome spondylodysplastic type 3 (EDSSPD3, OMIM 612350) is an inherited recessive connective tissue disorder that is caused by loss of function of SLC39A13/ZIP13, a zinc transporter belonging to the Slc39a/ZIP family." (PMID 38609428, 2024). "Recessive loss-of-function variants in SLC39A13, a putative zinc transporter gene, were first associated with a connective tissue disorder that is now called “Ehlers–Danlos syndrome, spondylodysplastic form type 3” (SCD-EDS, OMIM 612350) in 2008." (PMID 32295219, 2020). "A connective tissue disorder associated with recessive biallelic variants in SLC39A13, and a mouse knock-out model for the same gene, were described in 2008 by two separate but collaborating groups." (PMID 32295219, 2020). "Here we report that knockout of Slc39a13 in mice results in a generalized skeletal and connective tissue disorder, and that a homozygous loss of function mutation in SLC39A13 is found in a unique type of the EDS in human subjects." (PMID 18985159, 2008). "Growth and stature—postnatal reduced linear growth seems to be a salient and consistent feature of SLC39A13 deficiency; this is in contrast to other types of connective tissue disease and EDS types, where short stature is not a prominent feature." (PMID 32295219, 2020). "Thus, our results allow to establish a genetic and functional link between the Zn transporter Slc39a13 and connective tissue development, showing the usefulness of the Slc39a13-KO mouse as a novel animal model for human connective tissue diseases." (PMID 18985159, 2008). "It is also noteworthy that the physical strength of the ocular bulbs in Slc39a13-KO mice was reduced (data not shown); loss of Slc39a13 may be pathogenically linked to connective tissue disorders associated with fragile eyes." (PMID 18985159, 2008).
tumor (3 papers, 2021 to 2026). "Fibroblasts with high SLC39A13 expression were linked to immunosuppressive tumor environments characterized by reduced cytotoxic T-cell infiltration and increased immunosuppressive cells." (PMID 42187609, 2026).
SLC39A13 also shares sentences with these, for which no sentence is quoted: Obesity (5 papers); skeletal dysplasia (5); Arrhythmia (2); cardiovascular disease (2); fibrosarcoma (2); glaucoma (2); Insulin resistance (2); metabolic disease (2); metabolic syndrome (2); myopathy (2); Alzheimer disease (1); blue sclera (1); breast tumor (1); calcific aortic valve disease (1); diabetes (1); dwarfism (1); epidermodysplasia verruciformis (1); Fat atrophy (1); gastric adenocarcinoma (1); head and neck squamous cell carcinoma (1); heart disease (1); Hypodontia (1); infection (1); iron deficiency (1); ischemia (1); ischemic stroke (1); keratoconus (1); kidney disease (1); Liver Fibrosis (1); myocardial infarction (1).
A further 8 diseases each share a sentence with SLC39A13 in 1 paper.